ROCK1 (Rho associated coiled-coil containing protein kinase 1)
Diseases named in the same sentence as ROCK1 in open-access papers (continued):
Sharing a sentence is not in itself a finding about the gene and the disease.
cancer (continued). "Those associations between ROCK1 and most deletions were less common in ERG positive than in ERG negative cancers may be due to the different microenvironment in ERG positive cells." (PMID 31557128, 2019). "Similarly, higher expression of RhoA, ROCK1 and ROCK2 has been found in other types of cancer." (PMID 27203208, 2016). "Decreased expression of the miRNAs in cancer tissues leads to increased ROCK expression/activity and increased migration, invasion, or proliferation, which can be rescued by either overexpression of the miRNAs or inhibition of ROCK1 by either a ROCK inhibitor (Y27632) or ROCK1 siRNA molecules." (PMID 26725045, 2016). "Among the assessed mRNAs that were present in cancer-derived EVs and absent in MCF10A-derived EVs, several genes, including SNAIL1/2, TAZ, AXL, RHOA and ROCK1, are well known to promote cell motility." (PMID 33921957, 2021). "This suggested that even though the expression of ROCK1 had initially not been found to differ between cells transfected with empty vector or pROR2, the ROR2-induced increase in cancer cell invasiveness involved both, ROCK1 and ROCK2." (PMID 34911552, 2021). "For example, moderate to strong ROCK1 staining was seen in 63% of ERG IHC negative, but in 82% of ERG IHC positive cancers." (PMID 31557128, 2019). "Netarsudil, fedratinib, and osimertinib—specific inhibitors of ROCK1, JAK and EGFR, respectively—are FDA-approved antiproliferative drugs with similar IC50 values in both HeLa and U2OS cells, whereas quercetin and pranlukast do not show any effect on cancer cells viability and proliferation." (PMID 41325773, 2025).
cardiovascular disease (14 papers, 2013 to 2025). "The data showed increased expression of ROCK1 (but not RhoA) in all our experimental groups compared to control VECs, and appear to support previous finding regarding ROCK1 signaling involvement in the pathogenesis of various cardiovascular diseases." (PMID 38474293, 2024). "Inhibition of the activity of RhoA/ROCK-1 pathway would be beneficial in treating cardiovascular diseases since this pathway plays an important role in the development of these diseases." (PMID 34236817, 2022). "The RhoA/ROCK-1 pathway plays an important role in various cellular events involved in the pathogenesis of cardiovascular diseases as well as in the development of the effects of many vasoactive substances." (PMID 34236817, 2022). "In recent years, the RhoA/ROCK-1 signaling pathway aroused interest among researchers of cardiovascular diseases." (PMID 34236817, 2022). "Our findings suggest that the RhoA/ROCK signaling pathway is important in the pathogenesis of CAD, so the inhibition of the activity of RhoA/ROCK-1 pathway would be beneficial in treating cardiovascular diseases." (PMID 34236817, 2022). "Inhibition of ROCK1 has been shown to be a promising therapy for patients with cardiovascular disease." (PMID 34434664, 2021). "In this review, we focus on recent findings regarding ROCK signaling in the pathogenesis of cardiovascular disease, with a special focus on differences between ROCK1 and ROCK2 function." (PMID 26635606, 2015). "Research has confirmed that ROCK1 plays a vital role in cardiovascular disease." (PMID 35865967, 2022). "Importantly, in the context of cardiovascular disease and diabetic coronary dysfunction, both ROCK1 and ROCK2 are expressed in vascular endothelial and smooth muscle cells." (PMID 24059472, 2013). "The different functions of ROCK1 and ROCK2 in the pathogenesis of cardiovascular disease have been well documented." (PMID 28684968, 2017). "Similarly, many genes, including CALM2, PDCD4, TXNIP, CYP11B2, P2Y12, and ROCK1, have been identified as downstream targets of GAS5 in cardiovascular diseases." (PMID 38812041, 2024).
infection (9 papers, 2015 to 2025). The state of being infected such as from the introduction of a foreign agent such as serum, vaccine, antigenic substance or organism. "In uninfected control cells, endogenous ROCK1 exhibited a diffuse cytoplasmic distribution at 6 h, 12 h, or 48 h post-infection (hpi)." (PMID 40142587, 2025). "(ii) To further examine the role of ROCK1 in the early stage of MVC infection, ROCK1 knockdown using siRNA was performed in WRD cells." (PMID 40142587, 2025). "Our data demonstrated that in the early stage of MVC infection, MVC induced the activation of RhoA and ROCK1 as well as the early activation of pMLC2, and the peak activation was observed at 15 min post-infection, followed by a gradual decline." (PMID 40142587, 2025). "During this infection, ROCK1 was the primary ROCK family member activated in B cells, and its deletion alone resulted in profound pathology." (PMID 39903532, 2025). "Following MVC infection, ROCK1 co-localized with VP2 and translocated from the cytoplasm (12 hpi) to the nucleus (24 hpi)." (PMID 40142587, 2025). "Compared with MVC infection cells, ROCK1 and pMLC2/MLC2 ratio were decreased by 2.5-fold and 4-fold in pre-treated ROCK-siRNA cells, respectively." (PMID 40142587, 2025). "During the early stage of MVC infection, the RhoA/ROCK1/MLC2 signaling pathway is activated, resulting in TJ dissociation, Occludin exposure, and an increase in the permeability of the cell membrane, all of which facilitated MVC entry into host cells." (PMID 40142587, 2025). "In WRD cells, as MVC infection progressed from 6 h to 24 h, ROCK1 and VP2 gradually relocated from the cytoplasm to the nucleus." (PMID 40142587, 2025). "The topological plots showed that GNA13 and ARHGEF12 were significantly downregulated at 48 h post-infection, and these genes inhibit the Calcium signaling pathway by regulating ROCK1 and MYL12A." (PMID 37211158, 2023). "The infection of U937 cells with ROCK1 shRNA reduced the expression of ROCK1 and resulted in blockage in MC-3129-mediated ROCK1 cleavage/activation, PTEN activation and Akt inactivation." (PMID 29844397, 2018). "Levels of RhoA-GTP and ROCK1 activity were elevated upon ARV S1133 infection, while inhibition of RhoA and ROCK1 reduced autophagy and subsequent apoptosis." (PMID 25944062, 2015). "The results of our study indicated that the expression of RhoA-GTP is dramatically increased from 12 to 30 hr post-ARV S1133 infection, and the up-regulation of phosphorylated ROCK1 also showed a similar trend." (PMID 25944062, 2015). "The RhoA/ROCK/MLC signaling pathway was activated during the early stage of MVC infection, therefore, we investigated whether RhoA/ROCK1 signaling pathway is involved in MVC infection and entry." (PMID 40142587, 2025). "Moreover, we further identified that RhoA/ROCK1 inhibitors effectively block MVC infection." (PMID 40142587, 2025). "Moreover, numerous Ser/Thr kinases (STKs) were either increased (e.g., GRK2, ROCK2, ROCK1, PAK1) or decreased (e.g., BMP2K, TNIK, MYLK, and NRBP1) in expression in the patient samples, suggesting a widespread change in the kinome caused by pathogen infection." (PMID 38389037, 2024). "However, ROCK1 levels were significantly elevated during AD169 infection, suggesting that its degradation might depend on a protein/s that are encoded in the ULb’ region." (PMID 26599541, 2015). "(i) The WRD cells were pretreated for 1 h with specific inhibitors targeting RhoA (CCG-1423) or ROCK1 (Y27632), followed by MVC infection for 6 h, 12 h, and 18 h." (PMID 40142587, 2025). "In this study, we revealed for the first time that the kinase domain of the host protein ROCK1 directly interacts with the MVC VP2 protein, playing a key role in optimizing MVC infection." (PMID 40142587, 2025). "Given that the activation of the RhoA/ROCK1/MLC2 signaling pathway mediates TJ disassembly, we observed that this process occurs during the early stage of MVC infection." (PMID 40142587, 2025).
infection (continued). "To understand the correlation between the RhoA/ROCK1/MLC2/Occludin pathway and MVC infection, we analyzed the protein expression levels of Occludin in WRD cells infected with MVC and evaluated the effects of RhoA and ROCK1 inhibitors on its expression." (PMID 40142587, 2025). "We found that genes of the Calcium signaling pathway were all significantly downregulated at 24 and 48 h post-infection, such as GNA13, ARGHGEF12, ROHA, ROCK1, and MYL12A." (PMID 37211158, 2023). "Taken together, these experiments clearly demonstrate that RhoA/ROCK1 signaling plays an important role in the processes of autophagy and apoptosis that occur in the early and late stages of ARV S1133-infection of Vero cells." (PMID 25944062, 2015). "Taken together, these experiments clearly demonstrate that RhoA/ROCK1 signaling plays an important role in the processes of autophagy and apoptosis that occur in the early and late stages of ARV S1133 infection of cultured Vero cells." (PMID 25944062, 2015). "Collectively, our study provides the first evidence that there is a direct interaction between the structural protein VP2 of MVC and ROCK1, and that the tight junction protein Occludin can serve as a potential co-receptor for MVC infection, which may offer new targets for anti-MVC strategies." (PMID 40142587, 2025).
metabolic disease (6 papers, 2019 to 2025). A congenital disorder (due to inherited enzyme abnormality) or acquired (due to failure of a metabolically important organ) disorder resulting from an abnormal metabolic process. "The causal relationship between hepatic ROCK1 and metabolic disease has been investigated using a constitutively active ROCK1-specific mutant in the liver (L-CA-ROCK1), which increases ROCK1 activity 2-fold." (PMID 33633690, 2020). "To date, the most well-documented metabolic roles of ROCK1 are observed in liver, with clear connections demonstrated between hepatic ROCK1 overactivity and humans or rodents with metabolic disorders." (PMID 33633690, 2020). "Overall, studies have observed encouraging therapeutic potential of liver-specific ROCK1 inhibition in metabolic disease models, demonstrated by increased energy expenditure, improved insulin sensitivity, and attenuated lipid accumulation." (PMID 33633690, 2020). "Similar to adipose and liver, skeletal muscle ROCK1 expression and activity are elevated in rodent models of metabolic disease." (PMID 33633690, 2020). "Despite the glucose-lowering effects of ROCK1 inhibition in mouse models of metabolic disease, ROCK1 inhibition in cultured adipocytes impairs insulin-stimulated glucose uptake." (PMID 33633690, 2020). "Furthermore, dysregulated ROCK1 activity in either of these tissues results in metabolic disease phenotypes." (PMID 33633690, 2020). "Overall, tissue-specific approaches have made great strides in deciphering the many critical metabolic functions of ROCK1 and, ultimately, may facilitate the development of novel treatments for metabolic disorders." (PMID 33633690, 2020). "However, ROCK inhibitors have not yet been accepted for treating metabolic disorders due to potential systemic side effects, including hypotension caused by smooth muscle relaxation due to both ROCK1 and ROCK2 are similarly inhibited." (PMID 35769086, 2022). "Overall, ROCK1’s role in insulin signaling is complex, and the opposing effects of adipocyte-specific ROCK1 inhibition in healthy vs. pathological models, indicates an importance of basal ROCK1 activity to glucose homeostasis but also implicates its overactivity in metabolic disease pathologies." (PMID 33633690, 2020). "The ROCK family including ROCK1 and ROCK2 has recently emerged as a potential therapeutic target for the treatment of metabolic disorders." (PMID 35769086, 2022). "ROCK1 activity is elevated in the adipose tissue of DIO and db/db mice, and adipocyte-specific inhibition of ROCK1 rescues many metabolic disease pathologies." (PMID 33633690, 2020). "Mechanistically, our study provides novel insights into the molecular mechanism for Rho A/ROCK1 signaling in controlling CAVD, highlighting metabolic disorders in the pathogenesis of CAVD, and emphasizing a new button between abnormal hemodynamics and the metabolic phenotype." (PMID 36774349, 2023).
neurodegenerative disease (5 papers, 2014 to 2024). A disorder of the central nervous system characterized by gradual and progressive loss of neural tissue and neurologic function. "Recent studies demonstrate the crucial role of Rho-associated protein kinase-1 (ROCK-1) in various neurodegenerative diseases." (PMID 36943623, 2023). "The findings advance our understanding of ROCK1 function in lysosomal regulation and provide insights into the treatment of AD and other neurodegenerative diseases concerning lysosomal dysfunction." (PMID 39497162, 2024).
renal disease (4 papers, 2020 to 2025). "As such, we may reasonably suggest that targeting ROCK1 alone may not be adequate for attenuating tubular fibrosis, at least in UUO models, and the pathological contribution of ROCK1 to tubules may differ between DKD and other renal disease." (PMID 33101039, 2020).
animal disease (2 papers, 2018 to 2019). "Recent studies have shown that ROCK1 plays an important role in the regulation of apoptosis in various cell types and animal disease models." (PMID 29844397, 2018). "Moreover, studies have reported that the inhibition of ROCK1 increases survival in various animal disease models." (PMID 31263414, 2019). "Moreover, ROCK1 is reported to be cleaved and activated by a variety of mechanical stimuli and biochemical mediators in the regulation of apoptosis, as evidenced in various cell lines and animal disease models." (PMID 31263414, 2019).
heart disease (2 papers, 2015 to 2021). "Rho-associated kinase-1 (ROCK1) has been recognized for its pivotal role in heart diseases, different types of malignancy, and many neurological disorders." (PMID 34434664, 2021). "By crossbreeding the haploinsufficient Rnd3 with the global ROCK1-knockout (KO) mice, the augmented effects observed after TAC operation were strongly reduced, thus arguing for a role of Rnd3-ROCK1 signaling in the regulation of cardiomyocyte apoptosis in heart disease." (PMID 26635606, 2015).
retinopathy (2 papers, 2021 to 2022). "Injection of OPTC-overexpressing plasmids inhibited mRNA and the protein expression of RhoA/ROCK1 in the zebrafish model of hypoxia-induced retinopathy." (PMID 35006271, 2022).
infectious disease (1 paper, 2019). A disorder directly resulting from the presence and activity of a microbial, viral, or parasitic agent in humans. "DSG1 is directly linked with the cleavage of apoptotic proteins and via ROCK1 with MAPK signaling and infectious diseases (WDR1)." (PMID 31138830, 2019).
ROCK1 also shares sentences with these, for which no sentence is quoted: idiopathic pulmonary fibrosis (5 papers); diabetic cardiomyopathy (4); diabetic retinopathy (3); laryngeal squamous cell carcinoma (3); nasopharyngeal carcinoma (3); small cell lung carcinoma (3); airway hyperresponsiveness (2); Arthritis (2); autism spectrum disorder (2); chronic obstructive pulmonary disease (2); Clear Cell Renal Cell Carcinoma (2); E. coli infection (2); Ewing sarcoma (2); inflammation (2); lung diseases (2); metastatic disease (2); skin cancer (2); abortion (1); acute liver failure (1); acute respiratory distress syndrome (1); adenovirus infection (1); age-related macular degeneration (1); Airway obstruction (1); albuminuria (1); anaplasmosis (1); anemia (1); astrocytic tumor (1); breast tumor (1); bronchopulmonary dysplasia (1); cerebral cavernous malformation (1).
A further 62 diseases each share a sentence with ROCK1 in 1 paper.